STAT3 (signal transducer and activator of transcription 3)
Diseases named in the same sentence as STAT3 in open-access papers (continued):
Sharing a sentence is not in itself a finding about the gene and the disease.
tumor (continued). "We explore mechanistic insights into STAT3 signaling, including canonical and noncanonical pathways, epigenetic modifications, and its role in tumor progression, metastasis, and therapy resistance." (PMID 40166646, 2025). "Activation of STAT3 signaling plays a pivotal role in inducing ZEB1-mediated epithelial-mesenchymal transition (EMT) in various tumors, with STAT3 exerting a strong influence on the expression of ZEB1 in tumor cells." (PMID 40016707, 2025). "We observed that miR‐224‐5p could bind to and inhibit IL6ST expression and JAK2/STAT3 signaling pathway, and the inhibition of NSCLC tumor growth and JAK2/STAT3 pathway by miR‐224‐5p could be reversed by IL6ST overexpression." (PMID 39840666, 2025). "The results of network pharmacology and molecular docking analyses suggested that SSA may interact with BCL2, ESR1, HIF1A, and STAT3 as well as PI3K/AKT signalling pathways and inhibit tumour growth by promoting apoptosis." (PMID 39995416, 2025). "The tumor microenvironment (TME) is inherently inflammatory, driven by persistent production of pro-inflammatory cytokines (e.g., IL-6, IL-1β, TNF-α), chemokines, ROS, and activation of transcription factors such as NF-κB and STAT3." (PMID 41020838, 2025). "In particular, the effects of ADSC-EVs on the IL-6/STAT3 signaling pathway and microtubule organization—two key regulators of tumor growth and metastasis—have not been systematically explored." (PMID 41514893, 2025). "By interrupting the IL-6 → STAT3 or PI3K → immunosuppressive circuits, we might convert an immune-cold tumor into an immune-responsive one." (PMID 41374963, 2025). "These FAPα+CD144+ endoCAFs acquire vasculogenic mimicry(VM)capabilities to facilitate metastasis while promoting in situ tumor proliferation and invasion via the CD144-β-catenin-signal transducer and STAT3 signaling axis, exerting dual pro-tumorigenic functions." (PMID 40861469, 2025). "Additionally, HBx activates STAT3 to induce Twist, a gene promoting EMT, increasing tumor invasiveness and metastatic potential." (PMID 40060195, 2025). "Moreover, deletion of STAT3 resulted in increased IFN-γ and IL-12 expression in tumor myeloid cells." (PMID 40885734, 2025). "The fact that this relationship can be detected in TCGA‐PRAD tumor samples, expected to better represent the heterogeneity of each molecular subtype, strongly supports that the observed regulatory interaction between EGFR/STAT3 and ETV1 is likely to persist in vivo, independently of the tumor stage." (PMID 40808640, 2025). "Furthermore, cytoplasmic HMGB1-mediated STAT3 phosphorylation induced STAT3 target genes, including EMT phenotypes as well as PD-L1 expression, and contributed to tumor progression in mice." (PMID 40389855, 2025). "Unlike Arg1 and STAT3 inhibitors, which generally aim to suppress specific immune-suppressive pathways, IL-19 antibody therapy directly modulates the tumor microenvironment by addressing aberrant cytokine signaling." (PMID 40057744, 2025). "Similarly, in pancreatic ductal carcinoma, JAK/STAT3 also activates ROCK1, which leads to increased contractility, ECM remodeling, focal adhesion maturation and increased tumor progression and aggression." (PMID 41199904, 2025). "Syntaxin 6 induced tumour progression through an adaptor, RACK1, which recruited STAT3." (PMID 40293576, 2025). "utilized EVs derived from 4T1 tumor cells to encapsulate anti‐STAT3 short interfering RNA and DOX for treating triple‐negative breast cancer." (PMID 40600457, 2025). "Inhibition of IL-6 or its downstream pathways, including STAT3, could inhibit POSTN secretion and reduce tumor aggressiveness." (PMID 40426238, 2025). "Given that STAT3 is a critical regulator of immune responses in the TME, bile acid signaling in tumor cells could indirectly modulate immune cell infiltration." (PMID 41212437, 2025).
tumor (continued). "Increasing tumor size, the formation of an intra-tumoral vascular network, as well as the highly hypoxic microenvironment of GBM have been shown to skew the highly plastic CNS-macrophages towards the M2-TAM phenotype by an activation of the STAT3 pathway." (PMID 40075663, 2025). "Furthermore, the drug has been reported to inhibit key oncogenic signaling pathways (e.g., STAT3, NF-κB, c-FLIP, survivin) that contribute to tumor growth and metastasis." (PMID 40722758, 2025). "Other studies reported the axis of syntaxin 6/USF2/LC3B which promoted autophagy flux and tumour progression in HCC, showing that syntaxin 6 could trigger autophagy and affect the RACK1/STAT3 axis." (PMID 40293576, 2025). "In addition, circ0009910 knockdown inhibited tumor growth in vivo.Exosome-derived circ0009910 promotes PA progression and regulates EMT through the miR-106b-5p/STAT3 axis." (PMID 40324455, 2025). "Additionally, Gene Set Enrichment Analysis (GSEA) of tumor cells revealed that AB-329 induced the activation of immune and stress-related pathways (e.g., JAK/STAT3, apoptosis, TNF/NF-κB) while suppressing hypoxia and immunosuppressive signaling." (PMID 41009462, 2025). "Multiple cancer cell lines undergo apoptosis, and cell growth stops when STAT3 signalling is inhibited; this strategy discourages tumour regression and kills cancer cells while having no impact on normal cells." (PMID 40061959, 2025). "Additionally, PELP1 drives angiogenesis via the STAT3/VEGFA axis in endothelial cells, PELP1 KD significantly reducing tumor growth and angiogenesis in vivo." (PMID 41463382, 2025). "Besides, phosphorylated STAT3 dimerizes and translocates into the nucleus, where it influences cellular processes such as EMT, contributing to tumor initiation and progression." (PMID 40265014, 2025). "Finally, immunohistochemical analysis of xenograft tumor tissues showed that MWDT treatment in vivo reduced the expression of PTK2B, p-STAT3, and GPX4, confirming the inhibition of this signaling pathway within the tumor microenvironment." (PMID 41166024, 2025). "SRC proto-oncogene, non-receptor tyrosine kinase (Src) is a node of convergence for receptor mediated signaling pathways, activating substrates in the MAPK, JAK/Stat3, and PI3K/AKT pathways to promote tumor cell survival, proliferation and invasion in various cancers, including GBMs." (PMID 39919036, 2025). "Putting it together, our findings did not support Fusobacterium-associated M2 macrophage polarization in vivo, nor did they indicate that Fusobacterium promotes IL6/STAT3-mediated c-myc gene expression in tumor biopsies." (PMID 40895532, 2025). "Many of the pathways discussed, such as the IL-6/STAT3-hepcidin crosstalk, are well-studied in vitro; however, there is a lack of direct evidence from human tumour samples of different CRC subtypes." (PMID 41153383, 2025). "Here we have identified IL-6 as a CAF-derived factor that mediates crosstalk between the tumor stroma and tumor cells in ILC, leading to activation of the JAK/STAT3 signaling pathway, and increased migration, invasion and dissemination of ILC cells in zebrafish embryos." (PMID 40597443, 2025). "STING in tumor cells aids in the tumor rejection response in prostate cancer; however, its activity is frequently inhibited in these cells, partly through the JAK2 and STAT3 pathways." (PMID 41007720, 2025). "Beyond that, STAT3 and HMGN5 also colocalize in MDA-MB-231 TNBC tumor spheres." (PMID 40507264, 2025). "IL-6 signaling through JAK/STAT3 leads to epithelial-mesenchymal transition (EMT) in oral SCC and stemness of gliomas which may contribute to tumor progression." (PMID 40317079, 2025). "In summary, the anti-inflammatory potential of rutin is a major mechanism in the suppression of cancer, particularly through targeting NF-κB, signal transducer and activator of transcription 3 (STAT-3), and COX-2 pathways in tumor-related inflammatory environments." (PMID 41142938, 2025).
tumor (continued). "One study found that IGF2BP2 may work to promote tumor growth in PTC via interactions with APOE mRNA and the IL-6/JAK2/STAT3 pathway." (PMID 40243425, 2025). "Immunofluorescence staining demonstrated significant reductions in STAT3 and downstream proteins (VEGF, cyclin D1, c-Myc, BCL-2, and PD-L1) post-treatment, confirming D11-PROTAC’s ability to downregulate these proteins in tumor tissues, aligning with its cellular effects." (PMID 40118821, 2025). "However, persistent STAT3/STAT6 activation also contributes to T-cell exhaustion and dysfunction within the tumor microenvironment, posing a significant challenge for immunotherapy." (PMID 40243506, 2025). "These microbial-metabolic perturbations synergistically activate NF-κB and STAT3 signaling pathways, generating a pro-inflammatory cytokine milieu (IL-6, TNF-α, IL-1β) that establishes a tumor-promoting microenvironment through autocrine and paracrine cascades." (PMID 40919140, 2025). "Since STAT3 plays a critical role in inhibiting the expression of key immune activation regulators and enhancing the production of immunosuppressive factors, future studies should explore the impact of BZN on the tumor microenvironment." (PMID 40242440, 2025). "One such mechanism involves tumor-derived exosomal surface HSP72 that, through the HSP72-TLR axis, initiates the signaling for the T cell-dependent immunosuppressive function of MDSCs, ultimately leading to STAT3 activation." (PMID 40443670, 2025). "CD20+ subpopulation, known to secrete cytokines and chemokines that activate the STAT3/NF-κB signaling pathway, leading to increased expression of pro-inflammatory mediators, including IL-6, TNF-and IFN-γ, and MMP-9, which facilitate tumor invasion and metastasis." (PMID 40821783, 2025). "Tumours lacking Sesn3 exhibited increased activation of Akt and Stat3, along with elevated levels of stem cell markers such as Acta2, Cd44, and Cd133." (PMID 40361504, 2025). "In dendritic cells, JAK1/STAT3 signaling represses IL-12 production by inhibiting the recruitment of cyclin-dependent kinase 9/positive transcription elongation factor b (CDK9/P-TEFb) to the IL-12p35 promoter, thereby impairing anti-tumor immune responses." (PMID 40867898, 2025). "Beyond IL-23, STAT3 itself serves as a central regulator of MDSC function and tumor progression." (PMID 41228234, 2025). "However, M2-like TAMs enhance tumor cell survival by secreting IL-6 and TGF-β, which activate DNA repair pathways such as MGMT and PI3K/Akt/STAT3, leading to increased TMZ resistance." (PMID 41002423, 2025). "NF-κB is a well-known transcription factor that upregulates LCN2 levels in tumor cells under inflammatory conditions and ER stress, but the regulation of LCN2 by ATF4 and STAT3 in tumor biology has not yet been reported." (PMID 40109857, 2025). "Similarly, Bifidobacterium has been used as an adjuvant in hepatocellular carcinoma to inhibit tumor growth, increase IFN-γ secretion, and downregulate the JAK/STAT3 pathway." (PMID 41155242, 2025). "To further investigate the effect of OSMR mediated JAK/STAT3/CCL-2 pathway regulation on malignant behavior of GBM cells and macrophage polarization, we co cultured SF188 cells with THP-1 generated microglia to simulate the tumor microenvironment." (PMID 40161370, 2025). "Extensively activated within both neoplastic and non-neoplastic cells of the tumor microenvironment, STAT3 critically suppresses the expression of vital immune activators while concurrently fostering the generation of immunosuppressive factors." (PMID 40143965, 2025). "These exosomes enforce non-polarized macrophages to acquire the tumor-associated macrophages phenotype through HIF-1α and HIF-2α regulated SOCS4/SOCS5/STAT3 signaling pathway." (PMID 39928285, 2025).
tumor (continued). "Additionally, tumor-derived factors, such as VEGF, IL-6, and IL-10, can recruit MDSCs to the inflammatory TME, where they activate the STAT3 signaling pathway to produce more VEGF, establishing a positive feedback loop that promotes tumor angiogenesis." (PMID 40563367, 2025). "For example, lactate in the tumor microenvironment epigenetically upregulates the expression of VSIG4 in macrophages, which subsequently activates the JAK2/STAT3 pathway, enhances fatty acid oxidation and PPAR-γ expression, and drives polarization toward an immunosuppressive M2 phenotype." (PMID 40873588, 2025). "In the microenvironment of HB, the activation of the JAK2/STAT3 pathway promotes tumor angiogenesis by increasing the expression of angiogenic factors such as vascular endothelial growth factor (VEGF), which is crucial for tumor growth and metastasis." (PMID 41393242, 2025). "The positive rate of STAT3+ cells in tumor re-gions was significantly higher compared to region of normal breast tissue (p = 0.048)." (PMID 40636126, 2025). "Our results demonstrate that FXR upregulated HVEM expression via transcriptional activation, intracellular Akt, Erk1/2 and STAT3 signals, and cell cycle G1/S progression in NSCLC, thereby inhibiting the cytokine production and cytotoxic activity of tumor-infiltrating CD8+ T cells." (PMID 40985894, 2025). "The remaining four tRFs, including those with experimentally validated roles in tumor progression (e.g., GlyGCC-001-N-5i-1-33 targeting STAT3), were absent from OncotRF results." (PMID 40981380, 2025). "Activation of IL-6/STAT3, a classic signaling pathway in tumor cells, begins when IL-6 binds to IL-6Rα and gp130 receptor subunits on the membrane surface to form a complex that triggers phosphorylation of JAK kinase and ultimately activation of STAT3." (PMID 41041638, 2025). "These activations initiate downstream signaling cascades that encompass Ras and RhoGTPase, mitogen-activated protein kinases (MAPK), phosphoinositide 3-kinase (PI3K), and signal transducer and activator of transcription 3 (STAT3), thereby facilitating tumor cell survival and proliferation." (PMID 40867215, 2025). "Moreover, the NF-κB and STAT3 signaling pathways remain constantly activated in the TME, perpetuating pro-tumor inflammation." (PMID 41071399, 2025). "Similarly, STAT3 signaling is frequently upregulated in both TNBC and HR+ BC, where it promotes tumor progression by driving the accumulation of immunosuppressive cell types such as Tregs and MDSCs, which further inhibit effective immune responses." (PMID 40281554, 2025). "On the other hand, IL-17 could implement pro-tumor functions by activating oncogenic pathways like MAPK and STAT3 in tumor cells or via the interactions with other TME components." (PMID 40599775, 2025). "Hk2 KD in the tumor cells significantly decreased Pan-Kla and p-STAT3 levels in TAMs but not in other immunocytes, indicating that TAMs are the primary immune cells affected by tumor-derived lactate." (PMID 39883522, 2025). "Furthermore, tumor-secreted LCN2 can bind to SLC22A17 on tumor cells, activating JAK2/STAT3 signaling and promoting VEGF-A expression and release, which enhances tumor neovascularization." (PMID 41436606, 2025). "The analysis of STAT3 and LSD1 protein expression in OSCC patient samples from clinical proteomic tumor analysis consortium (CPTAC) identified that LSD1 and STAT3 protein expression increased with the progressive clinical stages and pathological grades in OSCC." (PMID 40246812, 2025). "Furthermore, TIM-3 inhibitors suppress IL-6/STAT3 signaling pathway activation in HCC cells, effectively inhibiting tumor proliferation and metastasis, which highlights their therapeutic potential against HCC." (PMID 40980688, 2025). "Compared with KTC tumors with hyperactive Stat3 and abundant integrin β3 expression, KTC-Stat3KO tumors that lack β3 expression were reported to be far less aggressive, supporting a role for the STAT3/β3 axis in tumor progression." (PMID 40701148, 2025).
tumor (continued). "Inhibition of p-STAT3 with C188-9, which is currently undergoing clinical trials for cancer treatment, reduces PD-L1 expression levels in tumor cells, enhances CD8+ T cell infiltration, and inhibits tumor growth." (PMID 40779629, 2025). "Furthermore, IL-6 or prostaglandin E2, which induces M2-TAM polarization by activating STAT3, STAT1, and STAT6 signaling pathways, can be secreted by tumor cells in response to cisplatin or carboplatin therapy." (PMID 40370720, 2025). "Targeting transcription factors (e.g., STAT3, AR, and Nrf2) or epigenetic regulators (e.g., EZH2 and PRMT) could facilitate a strategy that induces ferroptosis while simultaneously inhibiting tumor-promoting immunity." (PMID 41438466, 2025). "In addition to these intrinsic effects, STAT3 activation within the TME exacerbates immunosuppression by reducing NK cell recruitment and downregulating the expression of ligands required for tumor cell recognition and destruction." (PMID 39859231, 2025). "Therefore, we conclude that STAT3 inhibition is a viable means of treating KM-LUAD between initial tumor formation and tumor establishment." (PMID 40356899, 2025). "IL-6, though associated with tumor progression via STAT3 activation, can initiate negative feedback through SOCS3 or STAT3 degradation during acute stress." (PMID 41401147, 2025). "Therefore, pharmacologically interrupting the JAK2/STAT3 signaling cascade emerges as a rational and promising strategy for developing anti‐HCC therapies that are capable of targeting both inflammation and tumor progression in an integrated manner." (PMID 41200213, 2025). "KEVs encapsulating STAT3-targeting siRNA (siSTAT3) demonstrated enhanced structural integrity, targeted molecular recognition, and selective cytotoxicity in NSCLC cell lines, achieving substantial tumor growth inhibition in xenograft models." (PMID 40429976, 2025). "Actually, EGFR, ERK, STAT3, and FAK1 are also dominant players in tumorigenesis, we supported that TC2N upregulated phosphorylation levels of these oncoproteins, which in turn conferred oncogenic signals to promote tumor initiation." (PMID 39849581, 2025). "Furthermore, the development and survival of tumor cells are markedly inhibited by the combined suppression of FAK and STAT3." (PMID 40217305, 2025). "Notably, JAK2/STAT3 signaling supports CSC self‐renewal, which is crucial for tumor recurrence and resistance to treatment." (PMID 41049266, 2025). "LCA (and its high affinity conjugate TLCA) as a strong TGR5 agonist activates cAMP → STAT3/STAT6 and the inflammatory immunosuppressive pathway in the liver that bias macrophages toward immunosuppressive states, which establishes a pro-tumor microenvironment conducive to HCC progression." (PMID 41339918, 2025). "Moreover, Tumor, Normal, and Metastasis (TNM) plot analysis from TCGA showed that the expression of KDM1A network genes, including STAT3 and CTLA4, was higher in HNSCC clinical tumors than in normal human tissues." (PMID 40246812, 2025). "To investigate the potential mechanism of tumors in HFD mouse, we found that HFD mouse could activate the phosphorylation of JAK2, STAT3, and NF-κB p65 protein in TNBC tumor tissue." (PMID 40841364, 2025). "Furthermore, we also revealed that bavachin exhibited anti-tumor effects on laryngopharyngeal cells by regulating the MAPK and STAT3 signaling pathways." (PMID 40302804, 2025). "In tumor-infiltrating myeloid cells (TIMs), METTL3-mediated m6A modification of Jak1 mRNA enhances JAK1 protein translation efficiency through the m6A-YTHDF1 axis, leading to increased phosphorylation of STAT3." (PMID 40244180, 2025).